MEG3 (maternally expressed 3)
Diseases named in the same sentence as MEG3 in open-access papers (continued):
Sharing a sentence is not in itself a finding about the gene and the disease.
Obesity (continued). "This scenario prompted us to embark on this in-depth study with the aim of appraising the impact of MEG3 rs941576 SNP as a novel genetic marker of the risk and clinicopathological features of CRC as well as obesity-related CRC." (PMID 38704452, 2024). "Nevertheless, the current study results configure the potential clinical utility of MEG3/miR-27a/IGF1/IGFBP3 axis, especially miR-27a in screening and early diagnosis of obesity-associated CRC." (PMID 38704452, 2024). "MEG3 has been found to maintain glucose homeostasis and insulin signaling by protecting the hepatic endothelium against cellular senescence in obesity." (PMID 36979495, 2023). "The hepatic endothelial senescence promotes obesity-induced insulin resistance, which is tightly regulated by the expression of MEG3." (PMID 36979495, 2023). "Several studies have found that paternal fast food intake and obesity can lead to changes in DNA methylation and expression of Meg3 and Nnat in sperm, and Igf2/H19 in the offspring." (PMID 36386900, 2022). "Hepatic MEG3 overexpression via tail vein injection of MEG3-expressing AAV for 12 weeks in HFD mice also ameliorated obesity and hepatic lipid deposition." (PMID 36555704, 2022). "H19 expression had an inverse correlation while MEG3 expression had a positive correlation with obesity indices and HOMA-IR values in humans." (PMID 36555704, 2022). "Notably, H19, MEG3, GAS5, miR-26a-1-3p, and miR-376a-3p have been implicated in both asthma and obesity, suggesting their role in linking metabolic dysfunction with airway pathology." (PMID 41156032, 2025). "Interestingly, we observed a sex-dependent expression pattern: in the control group, girls showed higher expression levels than boys, whereas in the obesity group, boys had higher MEG3 expression than girls." (PMID 40806129, 2025). "However, the impact of MEG3 rs941576 on CRC susceptibility and its association with the clinical features and risk factors of CRC, including obesity are yet unexplored." (PMID 38704452, 2024). "MEG3 rs941576 was associated with magnified CRC risk in overall (OR (95% CI) 4.69(1.51–14.57), P = 0.0018) and stratified age and gender groups, but not with obesity-related CRC risk or MEG3/downstream targets’ expression." (PMID 38704452, 2024). "In addition, MEG3 expression in SAT was positively correlated with PPARγ and FAS expression, suggesting an essential role for MEG3 in obesity-related conditions." (PMID 34298896, 2021). "Furthermore, in a study carried out in samples of SAT and VAT adipose tissue from women, MEG3 expression in SAT had a significant relationship with obesity indices." (PMID 34298896, 2021). "Additionally, they observed that MEG3 knockdown induced endothelial senescence in vitro and cellular senescence of hepatic endothelium, promoting obesity-induced IR in obese mice." (PMID 34298896, 2021). "Taken together, the present study, for the first time, identifies changes in both mRNA and lncRNA levels contributing to HFD-induced obesity and indicates that lncRNA Meg3 might modulate several mRNAs via binding to microRNAs competitively." (PMID 32614631, 2020). "Therefore, the evidence suggests that reduced expression of MEG3 could be related to de novo lipogenesis present in children with obesity and IR." (PMID 40806129, 2025). "Consequently, our hypothesis posited the plausible clinical value of MEG3 downstream targets that regulate metabolic reprogramming in obesity-related CRC." (PMID 38704452, 2024). "Previous studies have reported a positive correlation between MEG3 and lipogenic genes, such as FASN and PPARG, in the subcutaneous adipose tissue of females with obesity." (PMID 40806129, 2025). "Our findings indicate that the expression of MEG3, FTO, and ATF4 is altered in children with obesity." (PMID 40806129, 2025).
Obesity (continued). "By constructing a ceRNA regulatory network, we have identified novel lncRNA-miRNA-mRNA interactions, highlighting MEG3, hsa-miR-7974, and SDC4 as central nodes in the molecular circuitry of obesity." (PMID 41199597, 2025). "This sex-specific shift in MEG3 expression from girls in the control group to boys in the obesity group may reflect differential regulatory mechanisms influenced by sex hormones, the onset of puberty, or distinct inflammatory responses in boys and girls with obesity." (PMID 40806129, 2025). "Our findings accentuate circulating MEG3/miR-27a/IGF1/IGFBP3, especially miR-27a as valuable markers for the early detection of obesity-related CRC." (PMID 38704452, 2024). "Our results in adipose tissue indicate that inhibition of release of PKCδI_C further reduces Gas5, while increasing the levels of Meg3 in DIO mice, suggesting a PKCδI-dependent pathway promoting the onset of type 2 diabetes in obesity." (PMID 39596898, 2024). "In this study, we further proceeded to evaluate the expression pattern and clinical relevance of circulating MEG3 in CRC and its ability to predict obesity-related CRC." (PMID 38704452, 2024). "The identification of a ceRNA network, where MEG3, AC020916.1, AC008738.7, XLOC_003001, and LOC112268144 act as molecular sponges for hsa-miR-7974 to regulate SDC4 expression, suggests potential new insights into the pathogenesis of obesity." (PMID 41199597, 2025). "In this study, the expression of MEG3, known to be involved in lipogenesis, was evaluated in PBMCs from children with obesity and compared with that of children without obesity." (PMID 40806129, 2025). "However, there is a paucity of literature about the clinical relevance of the MEG3/miR-27a/IGF1 and MEG3/miR-181a/SIRT1 co-expression networks in predicting obesity-related CRC." (PMID 38704452, 2024). "It would be of great significance to identify Meg3 as a significant ceRNA in BAT under HFD conditions and to determine the downstream mechanism whereby Meg3 in BAT affects the development of obesity and obesity-related diseases in response to an HFD." (PMID 32614631, 2020). "In this regard, we selected four maternally imprinted genes (MEST/PEG1, SNRPN/PEG4, NNAT/PEG5, and SGCE/PEG10), three paternally imprinted loci (H19-IG DMR, IGF2 DMR0, and MEG3-IG DMR) and one obesity related gene HIF3A to check the correlation of male BMI with sperm DNA methylation." (PMID 31246962, 2019). "Finally, MEG3 expression was higher in boys with obesity compared to boys without obesity (p = 0.002) and girls with obesity (p = 0.027), while girls with obesity showed higher MEG3 levels than boys without obesity (p = 0.014)." (PMID 40806129, 2025). "Moreover, the expression of the lncRNA MEG3 (p = 0.0197) was found to be higher among children with obesity than among those without obesity." (PMID 40806129, 2025). "Moreover, boys with obesity showed increased MEG3 expression compared to boys without obesity." (PMID 40806129, 2025). "MEG3 and FTO showed sex-dependent expression in children without obesity, while additional sex-related differences were observed for SREBP1, FASN, ACACA, FTO, and MEG3 in children with obesity." (PMID 40806129, 2025).
pituitary tumor (21 papers, 2005 to 2025). A benign or malignant neoplasm affecting the pituitary gland. "In pituitary tumors, hypermethylation of the MEG3 regulatory region is identified as an important mechanism associated with the loss of MEG3 expression." (PMID 30386180, 2018). "The MEG3 and HOX loci, identified in this study to be regulated by menin-dependent H3K4me3, assumes significance given that genes within these loci have been implicated in MEN1-like tumors types: silencing of MEG3 in pituitary tumors and HOX genes in parathyroid tumors." (PMID 22666422, 2012). "Recent studies have shown that MEG3 inhibits pituitary tumor invasiveness through the MIR-376B-3P/HMGA2 axis." (PMID 38827318, 2024). "For instance, levels of EMT markers were regulated after MEG3 overexpression: E‐cadherin was upregulated, while Twist, Slug and MMP‐7 were downregulated, suggesting that MEG3 suppressed pituitary tumor development by participating in the EMT process." (PMID 37904679, 2023). "MEG3 overexpression inhibits the proliferation, invasion and migration of pituitary tumor cells, which is achieved by negatively regulating miR-23b -3p and miR-23b -3p negatively regulating FOXO4." (PMID 36523500, 2022). "In human pituitary tumor-derived cells, enforced MEG3 expression was shown to significantly inhibit tumor growth." (PMID 30619763, 2018). "Hypermethylation of the MEG3 regulatory region is associated with the loss of MEG3 expression in non-functioning pituitary tumors." (PMID 40362297, 2025). "Furthermore, a previous article indicated that overexpression of MEG3 inhibited the proliferation, invasion and migration of pituitary tumour cells and accelerated apoptosis." (PMID 37303036, 2023). "Moreover, MEG3 promotes differentiation of porcine satellite cells by sponging miR-423-5p42 and is involved in pituitary tumor invasiveness." (PMID 33425489, 2021). "In clinically nonfunctioning pituitary tumors, it was demonstrated that hypermethylation of the MEG3 regulatory region was associated with the loss of MEG3 expression, providing evidence for a mechanism of MEG3 inactivation." (PMID 21489289, 2011). "MEG3, miR-376B-3p and HMGA2 form a signaling axis to regulate the invasion of pituitary tumor cells." (PMID 36523500, 2022). "MEG3, a maternally expressed, imprinted long noncoding RNA gene, was not expressed in functioning pituitary tumors and various human cancer cell lines, while its ectopic expression inhibited growth in human cancer cells, including HeLa, MCF‐7, and H4." (PMID 39346787, 2024). "Additionally, MEG3 plays a role in regulating cell proliferation, apoptosis, and the EMT process in pituitary tumors, positioning it as a promising target for the treatment of pituitary tumors." (PMID 41149459, 2025).
atherosclerosis (18 papers, 2019 to 2024). A disease characterized by the build-up of fatty material and calcium deposition in the arterial wall resulting in partial or complete occlusion of the arterial lumen. "In this study, we examined the role of Meg3 in developing atherosclerosis and regulating cellular senescence using loss-of-function and gain-of-function experiments in different mouse models." (PMID 38518516, 2024). "Human Meg3 transgenic mice were generated to examine the role of Meg3 gain-of-function in the development of atherosclerosis induced by PCSK9 overexpression." (PMID 38518516, 2024). "By analyzing our data and human and mouse data from the Gene Expression Omnibus database, we found that Meg3 expression was reduced in humans and mice with cardiovascular disease, indicating its potential role in atherosclerosis." (PMID 38518516, 2024). "Our studies indicate that Meg3 has complex roles in regulating cellular senescence of the vascular endothelium and the development of atherosclerosis in response to nutritional stress." (PMID 38518516, 2024). "In conclusion, we demonstrated that Meg3 promotes the development of atherosclerosis in response to a high-cholesterol diet." (PMID 38518516, 2024). "Together, these data demonstrated that Meg3 expression was reduced in humans and mice with cardiovascular disease, indicating its potential role in the pathogenesis of atherosclerosis." (PMID 38518516, 2024). "Future studies will provide great insight into the mechanisms by which Meg3 regulates atherosclerosis and cellular senescence of the vascular endothelium in a tissue-specific manner." (PMID 38518516, 2024). "Our data demonstrate that Meg3 has tissue-specific roles in cellular senescence and Meg3 expression promotes the development of atherosclerosis." (PMID 38518516, 2024). "Human Meg3 (hMeg3) transgenic mice were generated to examine the role of gain-of-function of Meg3 in the development of atherosclerosis." (PMID 38518516, 2024). "The experimental data suggest that lncRNA MEG3 regulates miR-361-5p and attenuates proliferation of VSMCs and apoptosis induced by oxLDL, which are involved in the development of atherosclerosis." (PMID 34940525, 2021). "To examine whether Meg3 is involved in the pathogenesis of atherosclerosis, we first examined Meg3 expression in humans with coronary artery disease (CAD)." (PMID 38518516, 2024). "In the current study, Meg3 deficiency did not cause cellular senescence in the aortas in the mouse model of atherosclerosis, although it still caused the cellular senescence of the hepatic endothelium." (PMID 38518516, 2024). "Statins may regulate the expression of several lncRNAs (e.g., LASER, MEG3, and H19) in patients with atherosclerosis." (PMID 37238718, 2023). "This evidence suggests that MEG3 could be used as a biomarker and therapeutic strategy to reduce and reverse atherosclerosis." (PMID 36968595, 2023). "The lncRNA MEG3/miR‐223/NLRP3 axis in atherosclerosis promotes endothelial cell pyroptosis." (PMID 33270361, 2021). "So, MEG3 promotes the development of atherosclerosis by increasing inflammation." (PMID 34552965, 2021). "It is of interest to determine whether TTR (directly or indirectly through HDL) regulates the MEG3/miR-223-3p/FBXW7/Notch1 signaling pathway in atherosclerosis." (PMID 34359938, 2021). "For instance, increased lncRNA MEG3 levels may play a critical role in regulating proliferation of endothelial cells and expression of type I collagen, type V collagen resulted in atherosclerosis." (PMID 31182968, 2019). "Thus, we demonstrated that Meg3 has multifaceted roles in cellular senescence and atherosclerosis." (PMID 38518516, 2024). "In addition, Meg3 regulates cellular senescence in a tissue-specific manner during atherosclerosis." (PMID 38518516, 2024). "LncRNA MEG3 acts as an endogenous sponge of miR-223 to increase the expression of NLRP3 and its related genes, thereby enhancing endothelial cell pyroptosis and atherosclerosis." (PMID 37498354, 2023).
atherosclerosis (continued). "Together, circRNA circDENND1B and the considered above lncRNA MALAT1, CHROME, GAS5, MEG3 function as ceRNAs and bind miRNAs that suppress the expression of ABCA1, which increases the level of ABCA1 mRNA and prevents the development of atherosclerosis." (PMID 34940525, 2021). "lncMEG3 is one of the lncRNAs responsible for pathological cardiac remodeling in atherosclerosis and ECM reconstruction, and MEG3 was shown to be downregulated in CAD." (PMID 34359938, 2021). "Our data suggest that the role of Meg3 in atherosclerosis is independent of lipid homeostasis and macrophage infiltration." (PMID 38518516, 2024). "We switched to an AAV8-mPCSK9-induced mouse model of atherosclerosis because the breeding pairs of and Meg3 KI mice often did not produce a litter or produce a smaller litter." (PMID 38518516, 2024). "Melatonin reduces the expression of lncRNA MEG3, and the low expression of lncRNA MEG3 inhibits the apoptosis of aortic endothelial cells via regulation of the miR-223/NLRP3 axis, thereby alleviating atherosclerosis." (PMID 36429069, 2022).
asthma (17 papers, 2019 to 2025). "Individuals carrying the variant genotypes have lower serum MEG3 level and are at increased risks of asthma and severe symptoms." (PMID 36726728, 2023). "We therefore perform the first study to evaluate the associations of SNPs in MEG3 with the risks of asthma using a case control study design." (PMID 36726728, 2023). "We selected a well-studied long non-coding RNA (lncRNA), MEG3, which is involved in multiple cellular functions and whose expression has been associated with asthma." (PMID 36726728, 2023). "We genotyped four single nucleotide polymorphisms (SNPs) in MEG3, rs7158663, rs3087918, rs11160608, and rs4081134, in 198 patients with asthma and 453 healthy controls and measured serum MEG3 expression level in a subset of controls." (PMID 36726728, 2023). "Studies in utero have shown that maternal famine was associated with higher methylation of IL10, LEP, ABCA1, GNASAS, and MEG3 genes, compared to the same-sex unexposed siblings, potentially increasing risk of asthma later in life." (PMID 32047643, 2019). "To explore whether miR-143-3p regulates role of lncRNA MEG3 in asthma, we performed loss-of-function experiments." (PMID 38824534, 2024). "MEG3 SNP rs7158663 is a genetic susceptibility locus for asthma in Taiwanese." (PMID 36726728, 2023). "Given that aberrant MEG3 expression is linked to asthma development, we hypothesize that genetic variants that affect MEG3 expression may be associated with the risk of developing asthma." (PMID 36726728, 2023). "The exact biological mechanisms underlying the roles of MEG3 in asthma pathogenesis remains unclear." (PMID 36726728, 2023). "In addition, we determine whether the selected SNPs influence the expression level of MEG3 in serum samples and provide strong genotype-gene expression correlation that explains the observed significant association between SNPs and asthma risk." (PMID 36726728, 2023). "We hypothesize that genetic variants in MEG3 may influence the risk of asthma." (PMID 36726728, 2023). "Since MEG3rs7158663 variant genotypes are associated with increased asthma risks, and asthma patients have lower serum MEG3 level than controls (Feng, Yang & Yan, 2020), we next determine whether there is a correlation between rs7158663 genotypes and serum MEG3 level." (PMID 36726728, 2023). "In vitro experiments also provide indirect evidence supporting that low MEG3 expression is linked to asthma development: treating human bronchial epithelial cells with cigarette smoke condensate or an environmental carcinogen nickel caused marked downregulation of MEG3 expression." (PMID 36726728, 2023). "Then, we investigated the relationship between lncRNA MEG3 and miR-143-3p in asthma by transfecting control-siRNA, MEG3-siRNA, inhibitor control, miR-143-3p inhibitor, MEG3-siRNA + inhibitor control, and MEG3-siRNA + miR-143-3p inhibitor to HASMCs." (PMID 38824534, 2024). "Recent studies have shown thatthe expression of lncRNA Maternally-Expressed Gene 3 (MEG3) was significantly reduced in the peripheral blood of asthma patients, and lncRNA MEG3 played important roles in asthma by regulating Treg/Th17 balance." (PMID 38824534, 2024). "Firstly, this study was mainly based on in vitro experiments to explore the role of lncRNA MEG3 in asthma, while in vivo studies need to be further validated by animal models." (PMID 38824534, 2024). "Our research is the first to elucidate the effects and mechanisms of lncRNA MEG3 and miR-143-3p on the proliferation and migration of HASMCs in airway remodeling in asthma." (PMID 38824534, 2024). "The lncRNA MEG3 has been reported to regulate Treg/Th17 homeostasis in asthma patients through targeting microRNA-17." (PMID 38824534, 2024). "This study also did not further explore the effects of FGF9 alone on HASMCs and on the protective effect of lncRNA MEG3 on asthma." (PMID 38824534, 2024).